ENTPD1 (ectonucleoside triphosphate diphosphohydrolase 1)
Diseases named in the same sentence as ENTPD1 in open-access papers (continued):
Sharing a sentence is not in itself a finding about the gene and the disease.
cancer (314 papers, 2011 to 2026). A tumor composed of atypical neoplastic, often pleomorphic cells that invade other tissues. "In detail, while the ADORA2B-PNP pair is associated to lower survival in uterus, P2RY4 axes with ENPP3 and ENTPD1 are associated to higher survival in the same cancer." (PMID 38723607, 2024). "Compared to other sites, bone metastases of both cancer types expressed higher levels of ENTPD1 and NT5E, which encode CD39 and CD73, respectively, and hydrolyze ATP to adenosine." (PMID 36186774, 2022). "Locus 10q24.1 also spans cancer-associated genes ENTPD1 and PDLIM1." (PMID 40278994, 2025). "The main mutation type of ENTPD1 in cancers was missense substitution with 15.89%." (PMID 34465393, 2021). "Thus, the ability of anthracyclines to cause bona fide ICD is lost when cancer cells are rendered autophagy-deficient by genetic manipulations or engineered to overexpress ectonucleoside triphosphate diphosphohydrolase 1 (ENTPD1, best known as CD39), an enzyme that degrades extracellular ATP." (PMID 26300886, 2015). "Other cancer-related genes located at the same locus include ENTPD1 (Ectonucleoside triphosphate diphosphohydrolase-1), and PDLIM1 (PDZ And LIM Domain 1)." (PMID 40278994, 2025). "ENTPD1 (CD39) was widely expressed in ovarian tissue, and was elevated in cancer tissue compared to normal tissue." (PMID 39431011, 2024). "In cancer treatment, genes Entpd1, Pgf, and Selenbp1 are being utilized as immunomodulatory targets." (PMID 38474724, 2024). "By reducing adenosine availability in the extracellular space, ENTPD1-targeted therapies seek to prevent metastasis and improve cancer immune response by restoring T-reg function." (PMID 36233136, 2022). "Ectonucleoside triphosphate diphosphohydrolase 1 (ENTPD1) has been proved to play a vital role in human cancers." (PMID 34465393, 2021). "The main sources of adenosine in cancer are typically CD39 and CD73, which are encoded by ENTPD1 and NT5E, respectively." (PMID 34307352, 2021). "It followed that ENTPD1 expression and its prognosis significance were discrepant among different cancer types." (PMID 34465393, 2021). "Over-expression of ENTPD1 has been shown in various cancers, which adversely affected the clinical outcome of patients." (PMID 34465393, 2021). "Based on these results, we hypothesize that the overexpression of GPR176 might exert a suppressive effect on cancer progression by modulating the activity of immune-stimulating factors, such as ENTPD1." (PMID 40689396, 2025). "Similarly, knockdown of ENTPD1 (CD39) in cancer cells and in mice yielded lower ATP consumption and increased T-Cell infiltration in tumors." (PMID 36233136, 2022). "The expression of ENTPD1 mRNA in human cancers was firstly evaluated." (PMID 34465393, 2021). "We then evaluated the protein expression of ENTPD1 in cancer tissues." (PMID 34465393, 2021). "It appeared that ENTPD1 played a vital role in different types of cancers." (PMID 34465393, 2021). "However, another research revealed the favorable function of ENTPD1 expression in process of cancers." (PMID 34465393, 2021). "However, ENTPD1 expression on Tregs is variable among healthy people, whereas it seems to be increased in patients with cancer." (PMID 32859050, 2020). "Notably, TNFSF4 and ENTPD1 are positively correlated with MATN3 across most cancers." (PMID 41004439, 2025). "Notably, CXCR3, CD8B, and ENTPD1 were identified as potent protective factors against six cancers." (PMID 38627900, 2024). "Notably, this included TGF-β (TGFB1, TGFB3), drivers of adenosine-mediated immune suppression (NT5E (CD73), ENTPD1 (CD39)), Wnt pathway ligands (WNT7A, WNT4), IL10 and drivers/markers of cancer-associated fibroblast activation (INHBA, WNT7A, TGFB1, FAP, PDGFRA, PDGFRB)." (PMID 39568014, 2024). "The results indicated that TACSTD2, ENTPD1, and SERPINA1 have some predictive ability for other cancer types, such as ATC and FTC, but their predictive power is not as strong as it is for PTC." (PMID 40520228, 2025).
cancer (continued). "Immune checkpoint therapy has shown considerable promise in treatment of cancers currently, many immune checkpoints are highly positively correlated with BAX, such as ENTPD1, CD80, and CD28." (PMID 39074253, 2024). "The ARMG risk score showed significantly positive relation with immunoinhibitors TGFB1 and VTCN1, and was negatively related with immunostimulators CD27, CD28, CD40LG, CD80, ENTPD1 and ICOS in pan-cancer." (PMID 38090588, 2023). "Ectonucleoside triphosphate diphosphohydrolase 1 (CD39) and ecto-5ʹ-nucleotidase (CD73) expressed at the cell surface of macrophages and cancer cells in the TME are responsible for the adenosine generation." (PMID 37740232, 2023). "In most cancers, CD86, TNFSF14, KLRK1, CD48, CD40LG, CD28, C10orf54, ENTPD1, CXCL12, and POLD2 are negatively correlated (p < 0.05)." (PMID 36081989, 2022). "ENTPD1 and NT5E, as important regulators of extracellular adenosine availability, facilitate evasion of the immune system by cancer cells." (PMID 36233136, 2022). "Ectonucleoside triphosphate diphosphohydrolase 1 (ENTPD1) is positively correlated with LYVE1, PDPN, and VEGFC in the LECs of patients with different cancers." (PMID 36067135, 2022). "For single immune checkpoint gene, the immune stimulator HMGB1 correlated positively with KIF11 in all human cancer types, and TNFSF4, BTN3A1, BTN3A2, and ENTPD1 correlated positively with KIF11 in most human cancer types." (PMID 36742345, 2022). "Future studies should be done, utilizing technology such as siRNA or CRISPR-KO/KD, to determine the direct role of ENTPD1, NTSE, and ADORA3 in cancer cell behavior." (PMID 36186774, 2022). "Through RNAseq database searches, we investigated the magnitude of expression of the genes involved in adenosinergic pathway, namely, CD39 (ENTPD1 gene), CD73 (NT5E gene), and CD38 (also responsible for eADO generation) among female HER2+ cancers." (PMID 34948316, 2021). "ENST00000311534 was significantly correlated with HMGB1, ENST00000326094 was significantly correlated with BTN3A1, CD160, TGFBR1, and IL6R, and ENST00000375991 was significantly correlated with CD276, ENTPD1, HMGB1, TLR4, KDR, and TGFBR1 among these 33 immune genes in more than 20 cancer types." (PMID 39766805, 2024). "ISCA1 was correlated with ENTPD1, HMGB1, TLR4, and TGFBR1 in more cancers." (PMID 39766805, 2024). "While CD276, ENTPD1, IDO1, LGALS9, and VSIR were commonly detected in the Stereo‐seq samples, only IDO1 and LGALS9 seemed to have higher and wider expression in the CSCC samples than in the non‐cancer samples." (PMID 35986392, 2022). "It followed that ENTPD1 did not affect the survival of female patients and those in early cancer stages." (PMID 34465393, 2021). "The correlation between levels of ENTPD1/CD39 in the host and CRC progression has been confirmed in orthotopic transplanted murine cancer models; while in clinical samples, lower levels of ENTPD1/CD39 mRNA in malignant CRC tissues correlates with prolonged survival and less invasiveness." (PMID 30941139, 2019). "Most of the knowledge in this area has been obtained by studying CD39/ENTPD1, the prototype member of this family, and evaluating the translational potential by either treating inflammation directly with recombinant proteins or by using antagonists to elicit immune responses in cancer." (PMID 41685236, 2026). "Interestingly, OLFML3, ENTPD1, and members of the EMILIN family are reported to be involved in regulating angiogenesis in other cancers, which is in line with the unique enrichment of angiogenic processes in the CAF-elevated N-glycoproteome observed in our study." (PMID 36671461, 2022).
infection (63 papers, 2009 to 2026). The state of being infected such as from the introduction of a foreign agent such as serum, vaccine, antigenic substance or organism. "Comparisons across the early- and late-stages of infection showed that cells from CHs had an early expression of genes associated with exhaustion (PDCD1, ENTPD1), and cytotoxicity, including NK-like genes NKG7, GNLY, KLRC2, and KLRC3 (encoding for NKG2C and NKG2E, respectively)." (PMID 36477661, 2022).
infectious disease (6 papers, 2015 to 2025). A disorder directly resulting from the presence and activity of a microbial, viral, or parasitic agent in humans. "Mounting evidence supports the role of ectonucleotidases, especially ENTPD1/CD39 and CD73, in the control of several inflammatory conditions, ranging from infectious disease, organ fibrosis to oncogenesis." (PMID 30941139, 2019).
cardiovascular diseases (3 papers, 2019 to 2025). "Interestingly, Tregs’ beneficial effects required intact CD39 (Ectonucleoside triphosphate diphosphohydrolase-1) signaling, suggesting that controlling purinergic metabolism may be an important Treg function in cardiovascular diseases." (PMID 35693830, 2022).
neurodegenerative disease (2 papers, 2020 to 2021). A disorder of the central nervous system characterized by gradual and progressive loss of neural tissue and neurologic function. "A mutation of ENTPD1 has been identified in Spastic paraplegia type 64 in individuals diagnosed with suspected neurodegenerative disease patients." (PMID 32041280, 2020).
ENTPD1 also shares sentences with these, for which no sentence is quoted: lung carcinoma (34 papers); AIDS (22); hepatocellular carcinoma (20); head and neck cancer (19); multiple sclerosis (18); pancreatic cancer (18); acute myeloid leukemia (10); asthma (10); cervical cancer (9); diabetes (9); myeloma (9); myocardial ischemia (9); atherosclerosis (8); colorectal tumors (8); immune dysfunction (8); autoimmune hepatitis (7); bladder cancer (7); chronic lymphocytic leukemia (7); colon adenocarcinoma (7); hepatitis B (7); leukemia (7); breast tumor (6); endometrial cancer (6); hematological malignancies (6); lymphoma (6); sarcoma (6); tuberculosis (6); B cell lymphoma (5); bacterial infection (5); breast (5).
A further 215 diseases each share a sentence with ENTPD1 in 5 papers or fewer.